NLRP2 (NLR family pyrin domain containing 2)
Diseases named in the same sentence as NLRP2 in open-access papers (continued):
Sharing a sentence is not in itself a finding about the gene and the disease.
cystinosis (2 papers, 2019 to 2024). Cystinosis is a metabolic disease characterized by an accumulation of cystine inside the lysosomes, causing damage in different organs and tissues, particularly in the kidneys and eyes. "In the light of these observations, our data demonstrating the upregulation of NLRP2 in cystinotic PTEC and the reduction of proinflammatory cytokines and chemokines in cystinotic PTEC silenced for NLRP2 shed a new light on mechanisms causing inflammation in cystinosis." (PMID 31709256, 2019). "Building on these findings, we next generated Ctns-/-Nlrp2-/- double KO mice to dissect the contribution of Nlrp2 in the development and progression of kidney disease in cystinosis." (PMID 38633264, 2024). "Herein, we have investigated the role of NLRP2 in vivo using a mouse model of cystinosis in which we have confirmed upregulation of Nlrp2 in the renal parenchyma." (PMID 38633264, 2024). "To extend our previous findings and investigate the in vivo role of NLRP2 in the pathogenesis of cystinosis, we first analysed the mRNA expression levels of Nlrp2 in whole kidney lysates obtained from Ctns-/- and wild type (WT) mice at different ages." (PMID 38633264, 2024). "Further confirming the upregulation of NLRP2 in cystinosis, we observed markedly higher NLRP2 protein levels in primary PTEC obtained from five cystinotic patients compared to PTEC from a healthy subject." (PMID 31709256, 2019). "Moreover, our findings unveil a novel potential mechanism involving NLRP2 overexpression in the pathogenesis of cystinosis." (PMID 31709256, 2019). "In chronic or genetic diseases, including cystinosis, the sustained overexpression of NLRP2 could contribute to the progression of renal failure by creating a vicious inflammatory cycle." (PMID 31709256, 2019). "We cannot therefore exclude that Nlrp2 may regulate additional pathways involved in the progression of cystinosis; further studies are needed to better understand the precise role of Nlrp2 in renal pathophysiology and specifically in cystinosis." (PMID 38633264, 2024). "In conclusion, our data show a partially protective effect of Nlrp2 inhibition in the cystinotic mouse model and provide additional rationale for testing anti-inflammatory strategies in addition to cysteamine to delay progression of kidney disease in patients with cystinosis." (PMID 38633264, 2024). "Generation of a PTEC-specific Nlrp2 knockout mouse would have allowed us to understand the exact role of Nlrp2 in PTEC and in the pathogenesis and progression of kidney disease in cystinosis." (PMID 38633264, 2024). "Furthermore, our data shed light on a potential mechanism involving NLRP2 overexpression in the pathogenesis of cystinosis and other tubulopathies, providing the rationale for novel targeted anti-inflammatory therapeutic strategies that may complement presently available conventional therapies." (PMID 31709256, 2019). "Our data reveals a previously unrecognized role for NLRP2 in PTEC and provide evidence of a novel mechanism involving NLRP2 overexpression in the pathogenesis of cystinosis." (PMID 31709256, 2019).
female infertility (2 papers, 2022). Diminished or absent ability of a female to achieve conception. "Several studies have demonstrated that mutations in SCMC‐related genes (TLE6, PADI6, NLRP2, NLRP5, and KHDC3L) cause human female infertility in the form of an exhibition of EEA and fragmentation." (PMID 35946397, 2022).
head and neck squamous cell carcinoma (2 papers, 2022 to 2024). A squamous cell carcinoma that arises from any of the following anatomic sites: lip and oral cavity, nasal cavity, paranasal sinuses, pharynx, larynx, and salivary glands. "High expression of NLRP2 was associated with high risk in head and neck squamous cell carcinoma." (PMID 35055428, 2022). "The potential utility of the NLRP2 gene in prognosticating survival in individuals diagnosed with head and neck squamous cell carcinoma is evident." (PMID 38312660, 2024).
infertile (2 papers, 2015 to 2021). "The NLR family has also been associated with incidents of early embryonic arrest (2- to 7-cell stage), resulting from infertile patients expressing NLRP2 and NLRP5 mutations which are illustrated as novel mutant genes." (PMID 34361119, 2021). "Since our granulosa parental cells were obtained from patients undergoing infertility treatment, there is a possibility that the granulosa cells carried genetic or epigenetic defects in the NLRP2 gene, thereby resulting in lower expression of NLRP2 in the iGRAs." (PMID 25889179, 2015).
leukemia (2 papers, 2020 to 2022). A malignant (clonal) hematologic disorder, involving hematopoietic stem cells and characterized by the presence of primitive or atypical myeloid or lymphoid cells in the bone marrow and the blood. "It has been reported that NLRP2 can be used as a marker of leukemia and has an important impact on the prognosis after stem cell transplantation." (PMID 31927533, 2020).
Miscarriage (2 papers, 2021 to 2024). A pregnancy that ends at a stage in which the fetus is incapable of surviving on its own, defined as the spontaneous loss of a fetus before the 22th week of pregnancy. "Other authors have found NLRP2 to be associated with idiopathic recurrent miscarriage." (PMID 34768839, 2021).
renal failure (2 papers, 2019 to 2022). "Overexpression of the NLRP family member NLRP2 was found to contribute to the progression of renal failure by creating a vicious inflammatory cycle and decreasing the apoptotic cell rate." (PMID 35055428, 2022).
viral infections (2 papers, 2016 to 2024). "Moving on, a notable increase was recorded in the NLR Family Pyrin Domain Containing 2 (NLRP2) DNA methylation in human astrocytes in response to viral infections, which may be more prominent in females than in males." (PMID 39451242, 2024).
adult-onset Still disease (1 paper, 2022). A rare inflammatory multisystem disorder characterized clinically by fever of unknown origin, arthralgia or arthritis, hyperleucocytosis, and typical skin rash. "Another 2017 paper showed that PBMCs taken from individuals with adult-onset Still’s disease (AOSD; an autoinflammatory condition), when compared to healthy controls, displayed elevated levels of NLRP3 mRNA and decreased expression of NLRP7, NLRP2, and NLRP12." (PMID 36298668, 2022).
celiac disease (1 paper, 2023). An autoimmune genetic disorder with an unknown pattern of inheritance that primarily affects the digestive tract. "According to a study on the role of small intestinal epithelial cells (IECs) in celiac disease, NLRP2/6/8, as inflammasome sensors, participate in an IFN-γ-circle in which NLRP2/6/8 receives signals from intestinal microbes and promotes the production of the downstream molecules IL-18 and IFN-γ." (PMID 37833958, 2023).
chronic kidney disease (1 paper, 2017). Impairment of the renal function secondary to chronic kidney damage persisting for three or more months. "Among the NLR family members (NLRP1, NLRP2, NLRP3, NLRP6, NLRP12, and NLRC4), NLRP3 deficient mice had less tubular injury, inflammation, and renal fibrosis in chronic kidney disease (CKD)." (PMID 29100270, 2017).
colonic cancers (1 paper, 2021). "In this study, we analyzed mononucleotide repeats in coding sequences of NLRP1, NLRP2, NLRP4 and NLRP9, and found 1, 1, 1 and 8 frameshift mutation (s) in gastric (GC) and colonic cancers (CRC), respectively." (PMID 34257569, 2021).
Fanconi syndrome (1 paper, 2024). "Our studies show that double knock out Ctns-/- Nlrp2-/- animals exhibit delayed development of Fanconi syndrome and kidney tissue damage." (PMID 38633264, 2024). "Collectively, these results indicate that albeit the invalidation of the Nlrp2 gene cannot completely rescue the Fanconi syndrome, it does result in partial improvement." (PMID 38633264, 2024). "We observed that although genetic ablation of Nlrp2 did not abolish the development of Fanconi syndrome or renal parenchymal lesions, it did delay it." (PMID 38633264, 2024).
glucosuria (1 paper, 2024). "When comparing Ctns-/- to Ctns-/-Nlrp2-/- mice, the onset of glucosuria and calciuria was delayed in the double KO animals (i.e. significant differences were observed at 4-6 months of age)." (PMID 38633264, 2024).
hepatic mesenchymal hamartoma (1 paper, 2021). "Many hepatic mesenchymal hamartoma (HMH) cases are associated with cytogenetic alterations at 19q13.4, a genomic region containing NLRP2 and NLRP7." (PMID 34068021, 2021).
kidney damage (1 paper, 2024). "The global kidney damage score confirms that genetic invalidation of Nlrp2 protected against the early development of kidney parenchymal lesions (p=0.009)." (PMID 38633264, 2024). "The global kidney damage score was significantly increased compared to 6-month old animals and was not attenuated by Nlrp2 invalidation." (PMID 38633264, 2024).
melanoma (1 paper, 2020). A malignant, usually aggressive tumor composed of atypical, neoplastic melanocytes. "To date, various inflammasomes, including NLRP1, NLRP2, NLRP3, absent in melanoma (AIM2) and NLRC4, have been identified." (PMID 31941010, 2020).
migraine (1 paper, 2021). "Also the roles of NLRP1, NLRP2 and AIM2 inflammasome complexes needs further study in migraine and its comorbid diseases." (PMID 34112082, 2021). "However, there is no data implying a relation between NLRP1 or NLRP2 inflammasome and migraine and/or CSD." (PMID 34112082, 2021).
mood disorder (1 paper, 2017). A cognitive disorder a disturbance in which the person's mood is hypothesized to be the main underlying feature. "Studies are required to elucidate the role of NLRP2 in BD and its tentative use as a biomarker for this, and possibly other mood disorders." (PMID 28117838, 2017).
myeloma (1 paper, 2022). "The NLRP2 gene, coding for a member of the nucleotide binding and leucine-rich repeat receptor (NLR), is an inhibitor of NF-κB pathway inhibitor which plays a key role in survival and proliferation of myeloma cells 94,95." (PMID 35198065, 2022).
myocardial infarction (1 paper, 2015). Gross necrosis of the myocardium, as a result of interruption of the blood supply to the area, as in coronary thrombosis. "CC homozygotes present a higher expression of the NLRP2 gene in leukocytes after myocardial infarction; therefore, this gene might play a role in the effects of rs12526453 on prognosis after myocardial infarction." (PMID 26086777, 2015). "Further verification of NLRP2 expression by means of qPCR confirmed that on the 1st day of myocardial infarction, it is up-regulated in the CC homozygotes group (in comparison to G-allele carrier patients) by a mean factor of 2.795 (S.E. range is 1.293–5.565; p<0.001)." (PMID 26086777, 2015). "However, given the established role of NLRP2 as an inflammatory process modulator and its higher expression in CC homozygotes, one may well imagine this phenomenon as the intermediating process in the effect of rs12526453 SNP on long term prognosis after myocardial infarction." (PMID 26086777, 2015).
omphalocele (1 paper, 2026). Omphalocele is an embryopathy classified in the group of abdominal celosomias and is characterized by a large hernia of the abdominal wall, centered on the umbilical cord, in which the protruding viscera are protected by a sac. "The first carried homozygous NLRP2 nonsense variants and experienced recurrent pregnancy loss and fetuses with multiple structural anomalies, including omphalocele, craniofacial dysmorphism, and cardiac defects." (PMID 41454780, 2026).
phenylketonuria (1 paper, 2009). Phenylketonuria (PKU) is the most common inborn error of amino acid metabolism and is characterized by mild to severe mental disability in untreated patients. "The inheritance of NLRP2-associated BWS has similarities to other autosomal recessive disorders in which homozygous mothers are well, but there is a high risk to their offspring (e.g. FHM and treated maternal phenylketonuria)." (PMID 19300480, 2009).
psoriasis (1 paper, 2025). An autoimmune condition characterized by red, well-delineated plaques with silvery scales that are usually on the extensor surfaces and scalp. "Research has indicated that the inflammasome inhibitor (NLRP2/AIM-3-IN-21) exhibited significant therapeutic potential in psoriasis, and effectively suppressed the expression levels of NLRP3, IL-17A, and AIM2 in psoriatic skin lesion tissues." (PMID 41383588, 2025).
Stroke (1 paper, 2021). Sudden impairment of blood flow to a part of the brain due to occlusion or rupture of an artery to the brain. "Additionally, other studies have shown that stroke is also associated with NLRP2 and NLRC4 In view of the accelerated progress in elucidating the mechanisms of inflammasomes, their use as therapeutic targets in stroke represents a promising future clinical application." (PMID 34233704, 2021). "We found that NLR family pyrin domain containing 3 (NLRP3) was the most studied, followed by NLRP1, NLRP2, and NLRC4 among the inflammasomes associated with stroke." (PMID 34233704, 2021). "The work focused on NLRP3 is the most systematic study, followed by NLRP1, NLRP2, and NLRC4 among the inflammasomes associated with stroke." (PMID 34233704, 2021).
tumor (21 papers, 2012 to 2025). "All IFC genes, except for NLRP2, showed significant elevated levels in tumor samples than in normal samples (Mann–Whitney U test p < 0.05)." (PMID 39588117, 2024). "In this study, we found that the pyroptosis genes including GSDMB, GSDME, NLRC4, NLRP2 and GZMA were hazardous genes in AML, and the genes of proinflammatory cytokines such as IL6 and TNF were found to be protective genes which maybe related with tumor microenvironment." (PMID 36553549, 2022).
infection (7 papers, 2010 to 2023). The state of being infected such as from the introduction of a foreign agent such as serum, vaccine, antigenic substance or organism. "At these conditions only one gene was detected as significantly up-regulated after infection, NLRP2, and four genes were down-regulated (ALDH3A1, CXCL8, IL1R2, KRT15)." (PMID 34785679, 2021). "In the context of molecular sex differences, NLRP2 showed sex-specific differences in both DNA methylation and gene expression across multiple infection-relevant tissues." (PMID 34895312, 2021). "As Francisella novicida U112 (Fn U112) does not activate the NLRP2 inflammasome, we tested whether FnU112 infection activates an NLRP332 inflammasome using the well-established inflammasome reconstitution assay." (PMID 32983094, 2020). "Several Nod-like receptor (NLR) family genes (nucleotide-binding oligomerization domain (NOD) 1, NOD2, NLRP2, NLRP3 and class II trans-activator (CIITA)) which act as intracellular sensors to detect cytosolic microbial components and "danger" signals were elevated upon infection." (PMID 21110886, 2010). "As we previously demonstrated, Fn U112 infection of NLRP3 inflammasome-reconstituted HEK293T cells elicited robust IL-1β production and cells lacking NLRP3, or expressing NLRP2, yielded IL-1β levels comparable to uninfected controls." (PMID 32983094, 2020).
cancer (6 papers, 2021 to 2025). A tumor composed of atypical neoplastic, often pleomorphic cells that invade other tissues. "Such genes showed a lower proportion of monoallelic vs biallelic expression in cancer cell lines than some other imprinted genes, e.g., SNRPN, SGCE, NLRP2, H19, and ANO1." (PMID 40414875, 2025). "In our study, drug-sensitivity analysis revealed that the expression of NLRP7, NLRP2, NOD1, and CASP6 was positively correlated with some or most drugs in the cancer therapeutic response portal database." (PMID 34226539, 2021).
neurological disorders (3 papers, 2017 to 2024). "Although our comprehension of the role of certain inflammasomes in CNS disorders has substantially improved throughout the past two decades, the causes of multiple number of NLRP2- related neurological disorders are indispensable to be further researched." (PMID 38722788, 2024). "Eventually, we found 15 proteins that may associate with NLRP2, representing promising therapeutic targets and signaling pathways in NLRP2 associated neurological disorders." (PMID 38722788, 2024).
brain disorder (1 paper, 2024). A disease affecting the brain or part of the brain. "In this overview, following clarification of the main aspects of NLRP2 research, we aimed to describe a set of proteins (connectome) that had been already identified in a broad spectrum of brain disorders, but still none of their actions were directly linked with NLRP2." (PMID 38722788, 2024).
kidney disease (1 paper, 2024). "Taken together, results of this study indicate that the genetic ablation of the Nlrp2 gene delays the onset of kidney disease in Ctns-/- mice by reducing inflammatory infiltration, interstitial fibrosis, tubular lesions and apoptosis." (PMID 38633264, 2024). "Consistent with previous findings, we have confirmed upregulation of several inflammatory mediators, including those modulated by NLRP2, namely Il6, Cxcl1 and Cxcl5 at early and late stages of the kidney disease." (PMID 38633264, 2024). "We found that Nlrp2 expression levels were significantly higher in Ctns-/- kidneys compared to WT kidneys, both in the early (3-8 months of age) and in the late stage (10-16 months of age) of renal disease." (PMID 38633264, 2024). "Based on these findings, we hypothesized that upregulation of NLRP2 in cystinotic kidneys plays a role in the development of the interstitial inflammation and fibrosis, contributing to the progression to the end-stage kidney disease." (PMID 38633264, 2024).
respiratory diseases (1 paper, 2021). "It has been reported that NLRP2 is connected with the development of arsenic-induced skin lesions, chromosomal damage and respiratory diseases." (PMID 34768839, 2021).
NLRP2 also shares sentences with these, for which no sentence is quoted: atherosclerosis (2 papers); Obesity (2); periodontal disease (2); type-2 diabetes (2); autism (1); Behçet's disease (1); chronic obstructive pulmonary disease (1); chronic pancreatitis (1); developmental delay (1); dyskeratosis congenita (1); genetic diseases (1); gingivitis (1); gout (1); influenza infection (1); metabolic disorders (1); metabolic dysfunction-associated steatotic liver disease (1); pancreatic diseases (1); Parkinson disease (1); Peri-Implantitis (1); primary progressive multiple sclerosis (1); psoriatic arthritis (1); sarcoma (1); type 2 diabetes mellitus (1).